PDGFRA (platelet derived growth factor receptor alpha)
Diseases named in the same sentence as PDGFRA in open-access papers (continued):
Sharing a sentence is not in itself a finding about the gene and the disease.
breast cancer (77 papers, 2004 to 2025). A primary or metastatic malignant neoplasm involving the breast. "Single-cell sequencing of cancer-associated fibroblasts from a genetic murine breast cancer model suggested that high PDGFRα expression marks a resting, local fibroblast population." (PMID 38980580, 2024). "High PDGFRα expression has been linked to aggressive subtypes of breast cancer including TNBC, and high PDGF-CC expression increases the risk of 5-year distant recurrence." (PMID 37496657, 2023). "On the other hand, downregulation of PDGFRα was associated with poor prognosis of breast cancer patients." (PMID 34769066, 2021). "We conclude that HCMV infection in breast tumors will occur mainly in tumor-associated fibroblasts and in breast cancer cells expressing PDGFRα." (PMID 34575976, 2021). "We conclude that HCMV infection in tumors will preferentially target tumor-associated fibroblasts and breast cancer cells expressing PDGFRα." (PMID 34575976, 2021). "This is consistent with other studies showing a relative loss of PDGFRα+ CAFs during breast cancer progression in mice." (PMID 34016130, 2021). "More importantly, BM-derived CAF recruiting decreased the percentage of PDGFRα positive CAFs, and decreased PDGFRα in breast cancer patients was associated with worse prognosis." (PMID 31130595, 2019). "In conclusion, we have found that the proteins c-KIT, VEGFR2 and PDGFRα, encoded by genes at 4q12, are associated to the St Gallen breast cancer subgroup TNBC." (PMID 25025175, 2014). "Overexpression of PDGFRα in breast cancer has been found to be associated with tumor progression and to be involved in the metastasis process." (PMID 25025175, 2014). "In GISTs (KIT and PDGFRA mutations), breast carcinoma (HER-2 amplification) and lung cancer (EGFR mutation), targeted therapy has yielded best results in cases with activating mutation or amplification of the respective gene." (PMID 15583695, 2004). "Aberrant PDGFRA expression is closely associated with decreased survival in HER2+ breast cancers." (PMID 36979654, 2023). "We focused on PDGFRα because its activation creates a metastatic phenotype including an increased migratory potential, which is linked to metastases in papillary thyroid cancer and breast cancer." (PMID 34575976, 2021). "The high expression of PDGFRα was associated with poor survival in breast cancer." (PMID 33568640, 2021). "PDGFRα has been found to be associated with breast cancer progression and metastasis." (PMID 25025175, 2014). "Furthermore, in a Stage II breast cancer tissue array from the National Cancer Institute coexpression of Twist1 and PDGFRα was significantly associated with patient survival, indicating the importance of this pathway in human breast tumor progression." (PMID 21725138, 2011). "An innovative and original study analyzing breast cancer growth in PDGF-CC knockout mice unraveled unexpected PDGFRα-dependent control of ER expression and tamoxifen sensitivity in breast cancer." (PMID 38980580, 2024). "High expression of PDGFRA in breast cancer cells is related to poor histological features such as lymph node metastasis, HER2 positivity, high histological grade, and triple-negative cancer subtype." (PMID 37120792, 2023). "We analyzed the difference in survival rates according to the expression of PDGFRA in HER2+ breast cancer patients and further investigated the efficacy of PDGFR inhibitors such as ponatinib or sunitinib for the treatment of TRZ-resistant breast cancer." (PMID 36979654, 2023). "We also explored the downstream signaling pathways of the PDGFC and PDGFRA complex in TRZ resistant breast cancer cells." (PMID 36979654, 2023). "Since high stromal PDGFRB expression is known to be correlated with shorter survival in breast cancer, we checked the expression levels of PDGFRA and PDGFRB in TRZ_S and TRZ_R derived from the parental BT474 cells." (PMID 36979654, 2023).
breast cancer (continued). "We also found that in MMTV-PyMT mammary tumor specimens integrin α11 is strongly associated in breast cancer specimens with a PDGFRβ+ CAF subset and to lower degrees with PDGFRα, α-SMA, NG2 and FAP." (PMID 35378690, 2022). "A causal role in HCMV infection was established because overexpressing PDGFRA in T-47D breast cancer and BCPAP thyroid cancer cells substantially increased infectivity." (PMID 34575976, 2021). "Increasing PDGFRA expression in T-47D breast cancer and BCPAP thyroid cancer cells markedly increased HCMV infection." (PMID 34575976, 2021). "Infectivity and productive infection of breast cancer cell lines with a low passage clinical HCMV isolate depended on the level of PDGFRα expression." (PMID 34575976, 2021). "Next, the expression of PTEN, p-AKT1, p-CREB, and PDGFRα in invasive breast cancer tissues and the corresponding adjacent normal tissues was assessed by Western blot." (PMID 33568640, 2021). "We investigated HCMV infection in human breast cancer cell lines compared to fibroblasts, a component of tumors, and the role of platelet-derived growth factor receptor-α (PDGFRα)." (PMID 34575976, 2021). "Three recent studies on breast cancer, suggest that PDGFRa expressing fibroblasts are resident fibroblasts also present in normal tissue, and that these fibroblasts are linked to a good prognosis." (PMID 31937798, 2020). "Another study identified three CAF subpopulations with distinct biomarkers in breast cancer: vCAFs with marker Nidogen-2, mCAFs with marker PDGFRα and developmental CAFs with marker SCRG-1." (PMID 33292666, 2020). "PDGFRα/β are both upregulated in multiple tumors, and PDGFRβ is correlated with poor survival in breast cancer." (PMID 33292666, 2020). "The aim of the present study was to explore the expression of PDGFRα, PDGFRβ and ligand PDGF-CC in breast cancer to elucidate if these proteins are associated with molecular surrogate subtypes, type of metastatic location and prognosis in breast cancer." (PMID 29380207, 2018). "High PDGFRα and PDGF-CC expression were linked to breast cancer with an aggressive biological phenotype, e.g. the TNBC subtype, and high PDGF-CC increased the risk of 5-year distant recurrence." (PMID 29380207, 2018). "In conclusion, we show that high expression of PDGFRα, PDGFRβ and ligand PDGF-CC is associated to several important prognostic patient and tumour characteristics in breast cancer, indicating a link to tumours with inherent biological aggressiveness." (PMID 29380207, 2018). "The two mCAF markers Fibulin-1 and PDGFRα identified a profuse infiltration of mCAFs in the tumor stroma of human breast cancer tissue." (PMID 30514914, 2018). "Here, we report an interaction between CXCR4 and PDGFRα in promoting chemoresistance in breast cancer cells." (PMID 28415580, 2017). "The remaining four CNVRs overlapped with genes ZFP14, JAK1, LPA, PDGFRA and were also associated with RFS in breast cancer." (PMID 29116104, 2017). "Taken together, these results indicate that PDGFRα plays a critical role in reversing PR-induced EMT in breast cancer cells through NT21MP." (PMID 28415580, 2017). "In terms of prognosis of breast cancer, high expression of HMGB2 and PDGFRA in breast cancer indicated poor prognosis, while high expression of HSD17B in breast cancer suggested the opposite effect." (PMID 29050221, 2017). "PDGF isoforms exert their biological functions through binding and activation of PDGFRα and PDGFRβ, which are involved in the progression of a number of tumors, including breast cancer." (PMID 28989976, 2017). "Similar to our findings, a positive association between EMT transcriptional regulators, Twist1 and Snail, as well as PDGFRα expression was shown to be necessary for invadopodia development in breast cancer cells." (PMID 27845909, 2016). "PDGFRα and PDGFRβ expression on breast cancer and the surrounding tumor stroma has been shown to be highly correlated with tumor aggressiveness and metastasis, respectively." (PMID 27931212, 2016).
breast cancer (continued). "For example, PDGFRα and β are two well-known receptors that participate in breast cancer progression." (PMID 27881889, 2016). "Immunofluorescence analyses of primary 4T1 mammary tumours demonstrated a homogenous distribution of PDGFRα‐positive fibroblasts, whilst it clearly demonstrates reduced levels of αSMA‐positive cells within hypoxic regions of the tumour." (PMID 26323721, 2015). "We also showed previously that knockdown of PDGFRα, or knockdown of both PDGFRs significantly inhibited migration but did not inhibit proliferation or promote apoptosis in our claudin-low murine mammary tumor cell line." (PMID 25253994, 2014). "Our previous study showed that murine claudin-low mammary tumor cells expressed elevated levels of PDGFRα and PDGFRβ compared to murine luminal mammary tumor cells." (PMID 25253994, 2014). "Namely, PDGFRα, Src, and metalloproteases localized in invadopodia are appealing, druggable targets for targeting invasion in breast cancer metastasis." (PMID 21725138, 2011). "As a direct target of Twist1 tightly associated with survival in human breast cancer patient tissue samples, PDGFRα is an especially appealing target for therapeutic intervention in breast cancer metastasis." (PMID 21725138, 2011). "Consistent with the western blot data, qRT-PCR analysis revealed that IGF-IR mRNA was significantly decreased in the mammary tumors following doxycycline withdrawal while the levels of PDGFRα and PDGFRβ mRNA were elevated at least 2.9-fold." (PMID 22070644, 2011). "As a first step, western blotting was performed for PDGFRα and PDGFRβ in primary mammary tumors (IGF-IR-dependent) and IGF-IR-dependent recurrent tumors of MTB-IGFIR transgenic mice." (PMID 22070644, 2011). "IGF-IR independent mammary tumors, previously shown to possess characteristics associated with EMT, were found to express elevated levels of PDGFRα and PDGFRβ." (PMID 22070644, 2011). "The aim of the present study was to investigate the role of PDGFRA in HER2+ breast cancer." (PMID 36979654, 2023). "We recently showed that the incidence of HCMV infection of breast cancer cells is considerably less than that of fibroblasts with higher infection dependent on the expression of platelet-derived growth factor receptor alpha (PDGFRα)." (PMID 35267456, 2022). "MSC‐derived CAFs in breast cancer are also functionally distinct from resident fibroblast‐derived CAFs, showing no expression of PDGFRα and associating with worse prognosis." (PMID 35533046, 2022). "However, little is known about the importance of PDGFRα expression on HCMV infection in breast cancer cells." (PMID 34575976, 2021). "Our murine data are also in agreement with findings in human breast cancer, showing reduced levels of PDGFRα and the concomitant increase in PDGFRβ expression as the disease progresses, which also acts as a strong marker of high-risk ductal carcinoma in situ (DCIS)." (PMID 34016130, 2021). "Inhibition of the oncogenic EMT process by targeting CXCR4/PDGFRα-mediated pathways using NT21MP may provide a novel therapeutic approach towards breast cancer." (PMID 28415580, 2017). "We tested this hypothesis by injecting the hypoxyprobe into mice bearing 4T1 mammary tumours and stained tumour sections for PDGFRα and αSMA." (PMID 26323721, 2015). "PDGFRα has recently been associated with basal B like cell lines, but to our knowledge, the expression of PDGFRα has not been correlated to a breast cancer subgroup in a clinical cohort before." (PMID 25025175, 2014). "The finding of increased Pdgfrα phosphorylation is of interest because autocrine Pdgf action is associated with TGF-β-induced epithelial–mesenchymal transition (EMT) in MMTV-Neu mammary tumours and because increased Pdgfrα and Pdgfrβ expression occur in late-stage, invasive human breast cancers." (PMID 25200860, 2014).
breast cancer (continued). "PTEN loss and expression of c-Kit, c-Met, HIF-1α, PDGFRA VEGFR2, and VEGF-A have been reported to be worse prognostic factors for breast cancer, whereas expression of IGF-1R, Bcl-2 and survivin are reportedly good prognostic factors for breast cancer." (PMID 24245483, 2013). "For example, the androgen (AR) and estrogen (both ESR1 and ESR2) nuclear hormone receptors are known to be relevant in prostate and breast cancers, and the alpha-type platelet-derived (PDGFRA) and epidermal (EGFR) growth factor receptors are recognised angiogenesis factors." (PMID 22558171, 2012). "In human specimens of breast cancer, both PDGFRα and β are expressed in the blood vessel wall." (PMID 27713269, 2010). "Another study, also linking loss of PDGFRα-positive cells to tumor progression, reported the accumulation of PDGFRα-negative bone marrow–derived fibroblasts at the primary tumor as well as the metastatic sites of the MMTV-PyMT transgenic mouse breast cancer model." (PMID 38980580, 2024). "Therefore, targeting the PDGFRA/STAT3/IL-6 pathway using PDGFRA inhibitors might serve as a therapeutic option to reduce tumor aggressiveness in HER2+ breast cancer." (PMID 36979654, 2023). "Furthermore, we analyzed the clinical implication of PDGFRA expression in HER2+ breast cancers." (PMID 36979654, 2023). "Thus, targeting CXCR4 to inhibit the PDGFRα signaling pathway with an appropriate therapeutic agent may represent a means of controlling the breast cancer progression." (PMID 28415580, 2017). "In breast cancer, CAF markers such as FAP, α-SMA, Vimentin, FSP1, PDGFRα, PDGFRβ, Caveolin-1, and PDPN have been validated." (PMID 39519118, 2024). "The results showed that HER2+ breast cancer patients with high PDGFRA expression had worse relapse-free survival (RFS, p = 0.02) than those with low PDGFRA expression." (PMID 36979654, 2023). "PDGFs and their receptors (PDGFRA and PDGFRB) are expressed in a variety of malignant tumor cells and tissues such as breast cancer and neuroendocrine tumors." (PMID 36979654, 2023). "PDGFRA expression is upregulated in TRZ-resistant cells and inversely correlated with HER2+ breast cancer patient survival." (PMID 36979654, 2023). "These analyses demonstrate that all six markers identify CAFs in breast cancer, and we therefore designed an antibody panel consisting of the 5 cell surface CAF markers: FAPα, PDGFRα, PDGFRβ, PDPN and CD26." (PMID 34016130, 2021). "Previous work in other cancers (e.g., papillary thyroid cancer, breast cancer, and melanoma) has demonstrated that EMT programs, which promote tumor invasion and metastases, are regulated by PDGFRA signal transduction." (PMID 33603171, 2021). "Our work shows a strong correlation between PDGFRA expression and IE antigen detection after viral exposure in HEL299 fibroblasts and breast cancer cell lines." (PMID 34575976, 2021). "We studied the effects of over-expressing PDGFRα protein in BCPAP thyroid cancer cells and T-47D breast cancer cells." (PMID 34575976, 2021). "This study aimed to evaluate the expression of PDGFRα, PDGFRβ and ligand PDGF-CC in breast cancer in relation to molecular subtypes and prognosis." (PMID 29380207, 2018). "In breast cancer, most studies of the PDGF signalling pathway examine the expression of PDGFRα and PDGFRβ." (PMID 29380207, 2018). "NT21MP inhibited tumor growth and the expression of PDGFRα, and EMT-associated proteins had similar expression patterns to the experimental results observed in vitro, suggesting NT21MP may inhibit tumor resistance by inhibiting the CXCR4/PDGFRα signaling mechanism in breast cancer." (PMID 28415580, 2017). "The inhibition of PDGFRα by PDGFRα inhibitors and NT21MP attenuated the SDF-1α-stimulated phosphorylation of AKT and ERK1/2 and breast cancer cell migration and had a synergistic effect compared with single treatment with either NT21MP or PDGFR inhibitor." (PMID 28415580, 2017).
breast cancer (continued). "For example, in breast cancer, the desmoplastic response appears to be mediated by PDGF-AA signaling in PDGFRα type CAF; this possibility is compatible with our findings." (PMID 26163388, 2015). "In this study, gene copy number and protein expression were evaluated for three RTKs as potential breast cancer drug targets: c-KIT, vascular endothelial growth factor receptor-2 (VEGFR2) and PDGFRα." (PMID 25025175, 2014). "To date, the clinical implication of PDGFRA expression in HER2+ breast cancers has not been fully elucidated yet." (PMID 36979654, 2023). "Tumour cell expression of PDGFRα is commonly up-regulated in lymph node metastases and asynchronous recurrences, whereas high expression of PDGF-CC is related to early breast cancer recurrence supporting an active role of the PDGF signalling pathway in tumour progression." (PMID 29380207, 2018). "In addition, in breast cancer, the desmoplastic response appears to be mediated by PDGF-AA signaling in PDGFRα type CAFs." (PMID 27881889, 2016). "However, the functional role of PDGFR alpha (PDGFRA) in HER2-positive (HER2+) breast cancer has not been fully clarified yet." (PMID 36979654, 2023). "In-depth researches showed that CD10+GPR77+ CAFs may correlate with chemoresistance in breast cancer and lung cancer; PDGFRα negative CAFs may correlate with poor prognosis in breast cancer." (PMID 33740980, 2021). "We present novel data on expression of PDGFRα, PDGFRβ and ligand PDGF-CC in primary breast tumours, synchronous lymph node metastasis and asynchronous recurrences in relation to St Gallen Molecular subtypes and long-term follow-up data in a large cohort of primary breast cancer patients." (PMID 29380207, 2018). "In vitro, the effects of NT21MP, CXCR4 and PDGFRα on tumor EMT were assessed by relative quantitative real-time reverse transcription–polymerase chain reaction, western blot and biological activity in breast cancer cell lines expressing high or low levels of CXCR4." (PMID 28415580, 2017). "We used a breast cancer cell line that does not express CXCR4 to determine whether NT21MP inhibits the EMT process through the CXCR4/PDGFRα signaling pathway and demonstrated that NT21MP targeted CXCR4, inhibits EMT, and inhibits tumor progression." (PMID 28415580, 2017). "We also identified PDGFRα as an effector that mediates CXCR4-induced EMT, suggesting that targeting the CXCR4-PDGFRα-PI3K pathway may be beneficial to NT21MP-reversed drug resistance in breast cancer." (PMID 28415580, 2017). "Also, a recent study showed that mRNAs encoding PDGFRα, PDGFRβ and their ligand PDGF-C were highly expressed in basal B subtype of breast cancer cell lines with mesenchymal properties but not in luminal-like cell counterparts with more epithelial features." (PMID 25025175, 2014). "The aim of this study was to analyze protein expression and gene copy number for c-KIT, VEGFR2 and PDGFRα in order to elucidate if there is a correlation between the copy number of these genes, their protein expression, and the prognosis of breast cancer in the TNBC subgroup compared to non-TNBC." (PMID 25025175, 2014). "In addition, knockdown of PDGFRα or PDGFRβ significantly reduced migration but not proliferation of the claudin-low mammary tumor cells." (PMID 25253994, 2014). "It was shown that breast cancer cells induce PDGFRβ, but not PDGFRα expression in the adjacent ECs." (PMID 27713269, 2010). "In the current study, we discussed whether platelet-derived growth factor receptor-α (PDGFRα) is required for SDF-1α/CXCR4 signaling and explored how NT21MP contributes to reversing CXCR4-induced EMT to provide insight into the potential efficacy of NT21MP as adjuvant chemotherapy for breast cancer." (PMID 28415580, 2017). "Unlike thyroid and breast cancers, we did not identify PDGFRA regulation of TWIST1 or SNAIL expression (data not shown) in GIST, whereas SLUG expression was modulated by PDGFRA activation." (PMID 33603171, 2021).
breast cancer (continued). "In contrast, infection of most breast cancer cells by HCMV, especially those with low PDGFRα expression, does not contribute to the pro-inflammatory environment through cytokine/chemokine/growth factor release." (PMID 34575976, 2021).